ZNF223 (zinc finger protein 223)
Description:
May be involved in transcriptional regulation.
Tractability: PROTAC: ubiquitination databases record sites on it.
Gene: Protein-coding gene on chromosome 19 (44,051,367 to 44,067,999, forward strand). Ensembl gene ENSG00000178386.
Subcellular location: Nucleus
Subcellular location (Human Protein Atlas): Nucleoplasm; Mitochondria
Pathways (Reactome):
Gene expression (Transcription): Generic Transcription Pathway
Gene Ontology:
Molecular function: protein binding; DNA binding; DNA-binding transcription factor activity; sequence-specific DNA binding
Biological process: negative regulation of DNA-templated transcription; regulation of DNA-templated transcription
Cellular component: nucleus
Genetic constraint (gnomAD): Loss-of-function variants: 9 observed, 12.52 expected, observed/expected ratio (o/e) 0.72, 90% interval 0.43 to 1.25. The upper end of that interval is the gene's LOEUF score, 1.25, which puts it in group 5 of 6, group 1 being the genes least tolerant of losing a copy. Missense variants: 443 observed, 536.33 expected, observed/expected ratio (o/e) 0.83, 90% interval 0.76 to 0.89. Synonymous variants: 150 observed, 185.33 expected, observed/expected ratio (o/e) 0.81, 90% interval 0.71 to 0.93.
Homologues: Orthologues: chimpanzee ZNF223 (99% identical). Paralogues in human: ZNF155 (79% identical), ZNF222 (78% identical), ZNF230 (78% identical), ZNF233 (45% identical), ZNF285 (40% identical), ZNF214 (40% identical), ZNF527 (38% identical), ZKSCAN7 (37% identical), ZNF852 (36% identical), ZNF34 (36% identical), ZNF572 (35% identical), ZNF287 (35% identical), and 38 more.
Diseases named in the same sentence as ZNF223 in open-access papers:
ZNF223 is named in the same sentence as 1 disease in open-access papers, as found by Europe PMC text mining. Sharing a sentence is not in itself a finding about the gene and the disease. The quoted sentences say what the papers report.
ovarian carcinoma (1 paper, 2022). A malignant neoplasm originating from the surface ovarian epithelium. "ZNF223 upregulation has been associated with a subset of ovarian carcinomas." (PMID 36291758, 2022).